STAT3 (signal transducer and activator of transcription 3)
Diseases named in the same sentence as STAT3 in open-access papers (continued):
Sharing a sentence is not in itself a finding about the gene and the disease.
liver fibrosis (continued). "Noticeably, one of the Stat3 signaling cytokine with pro-fibrogenic properties is IL17A, enhancing activation of hepatic myofibroblasts either directly or through IL6 secretion and collected evidences indicate the contribution of activated STAT3 in liver fibrosis." (PMID 30346985, 2018). "Liver injury, serum bile acid concentration, hepatic fibrosis, and carcinogenesis were enhanced by the combination of simultaneous damage in line with activation of c-Jun N-terminal kinase (JNK), proto-oncogene c-Jun, and Signal transducer and activator of transcription 3 (STAT3)." (PMID 28881751, 2017). "Moreover, we demonstrated that targeting JAK/STAT3 through pretreatment of UC-MSCs with a specific JAK inhibitor AG490, could protect UC-MSCs from senescence and further enhance the therapeutic efficacy in liver fibrosis." (PMID 37507381, 2023). "However, its role in regulation of EGFR and STAT3 during liver fibrosis has not been investigated." (PMID 26550019, 2015). "However, the application of PL for the treatment of liver fibrosis has not been evaluated in liver fibrosis model, especially the regulation of EGFR/STAT3 pathway in fibrotic liver." (PMID 26550019, 2015). "Although the effect of BM-MSCs on IL6/STAT3 pathway was conducted in cancer and has shown that MSCs could promote progression of cancer through activation of IL6/STAT3 pathway, the immunomodulatory role of BM-MSCs on IL17A/IL6/STAT3 was not fully elucidated in liver fibrosis." (PMID 30346985, 2018).
lung adenocarcinoma (196 papers, 2008 to 2026). A carcinoma that arises from the lung and is characterized by the presence of malignant glandular epithelial cells. "Consistently, B7-H3 deletion has been shown to reduce the phosphorylation levels of AKT and the signal transducer and activator of transcription 3 (STAT3) while increasing susceptibility to EGFR tyrosine kinase inhibitors in lung adenocarcinoma cells." (PMID 40004194, 2025). "We also analyzed the association between SHH, DUSP13B, and p‐STAT3 proteins in lung adenocarcinoma tissues and found that p‐STAT3 was significantly positively correlated with SHH but negatively correlated with DUSP13B." (PMID 39721017, 2025). "In the third cohort, we determined the KRAS mutation status and the expression levels of CD47, p-STAT3, and miR-34a in 100 pairs of lung adenocarcinoma and normal tissue samples." (PMID 36413402, 2023). "Dominant-negative STAT3 has been shown to reduce IL-6-induced vascular permeability associated with malignant pleural effusion in lung adenocarcinoma and decrease IgG-mediated vascular permeability during acute lung injury." (PMID 34542605, 2021). "The role of tumor-cell intrinsic STAT3 in cancer-associated inflammation has also been investigated in a urethane-induced model of lung adenocarcinoma, where epithelium-specific ablation of STAT3 significantly reduces carcinogen-induced lung tumorigenesis." (PMID 34944848, 2021). "A similar observation was reported in KRAS mutation induced lung adenocarcinoma, in which disruption of STAT3 induced tumorigenesis." (PMID 34047814, 2021). "The results showed that high levels of STAT3 expression were associated with shorter progression‐free survival durations in patients with lung adenocarcinoma." (PMID 32022328, 2020). "IL-11, a member of the IL-6 family, is upregulated in cisplatin-stimulated cancer-associated fibroblasts, and then IL-11 activates the STAT3 signaling pathway, leading to lung adenocarcinoma cell resistance to cisplatin." (PMID 32872659, 2020). "In lung adenocarcinoma, MPC1 deficiency accelerates lung adenocarcinoma progression through the STAT3 pathway." (PMID 32851100, 2020). "For example, STAT3 mediates the oncogenic effects of EGFR kinase domain mutations in human lung adenocarcinoma." (PMID 31092229, 2019). "Although knockdown of CD109 in human keratinocytes and lung adenocarcinoma cells downregulates STAT3 signaling in vitro, the CD109-deficient mice displayed opposite results." (PMID 29625613, 2018). "Altogether, TF was clearly shown to be regulated by IL-6/Stat3 signaling and involved in the formation of lung adenocarcinoma-associated MPE through modulation of vascular permeability in the tumor microenvironment." (PMID 24086497, 2013). "For example, persistently activated STAT3 is found in 50% of lung adenocarcinomas and is primarily observed in tumors harboring mutations in the epidermal growth factor receptor (EGFR)." (PMID 21533169, 2011). "Phosphorylated Stat3/5 appears to be particularly important for survival of human lung adenocarcinoma cells harboring certain EGFR mutations." (PMID 18461184, 2008). "Possible candidates to undergo such mutations include a multitude of gene products described in studies of human lung tumors, some of these studies have implicated the EGFR/IL-6/Stat3 pathway in the pathogenesis of lung adenocarcinomas." (PMID 18461184, 2008). "Moreover, a higher expression rate of p‐STAT3 protein was observed in EGFR mutated‐type lung adenocarcinoma tissues (P = 0.029)." (PMID 39721017, 2025). "The association among expression of SHH, DUSP13B, and p‐STAT3 proteins in lung adenocarcinoma." (PMID 39721017, 2025). "Besides, RIPK4 is associated with STAT3 signaling that is activated in tumor metastasis by regulating extracellular matrix remodeling enzymes in lung adenocarcinoma." (PMID 34124253, 2021). "Furthermore, in smokers with KRAS mutation, lung adenocarcinoma STAT3 correlated with poor survival and advanced malignancy." (PMID 34047814, 2021).
lung adenocarcinoma (continued). "Moreover, somatic-activating mutations in EGFR resulted in STAT3 over-activation through IL-6 production in human lung adenocarcinomas." (PMID 27861147, 2017). "Importantly, the level of IL-6 was positively associated with the level of STAT3 phosphorylation in lung adenocarcinoma tissues when the values for each individual patient were plotted (p<0.005)." (PMID 24789104, 2014). "Overall, these findings clearly confirmed that inhibition of STAT3 activation played an important role for GMI in inducing apoptosis in human lung adenocarcinoma cells." (PMID 41438583, 2026). "Western blot analysis was performed to assess the levels of phosphorylated STAT3 (p-STAT3, Tyr705) as a marker of activated STAT3 in lung adenocarcinoma cell lines treated with GMI." (PMID 41438583, 2026). "To further investigate the effects of QSFZYL combined with IFN-γ on the JAK2/STAT3 signaling pathway in lung adenocarcinoma, we performed qPCR analysis for JAK2 and STAT3 in tumor tissues of mice from each intervention group." (PMID 40642092, 2025). "We then utilized the GEPIA2 online platform to examine the correlation among the mRNA levels of SHH, GLI1, DUSP13B, and STAT3 in lung adenocarcinoma tissues from the TCGA dataset." (PMID 39721017, 2025). "In lung adenocarcinoma, p‐STAT3 is positively correlated with SHH but negatively correlated with DUSP13B." (PMID 39721017, 2025). "It has previously been reported that IL‐11 promotes tumour progression and EMT in lung adenocarcinoma through the activation of the STAT3/HIF‐1α/EMT signalling pathways." (PMID 40673604, 2025). "For example, the cancer-associated fibroblasts treated with cisplatin simulated IL-11 upregulated and subsequently activated STAT3, which finally promotes the lung adenocarcinoma cell resistance to cisplatin." (PMID 38245798, 2024). "A possible mechanism involves EGFR activation of epithelial-mesenchymal transformation via protein kinases and STAT3 activation by leukocyte hormone-6 to promote brain metastasis in lung adenocarcinoma." (PMID 38605303, 2024). "This indicates that GM-CSF secretion from lung adenocarcinoma cells can stimulate the activation of STAT3/STAT6 signaling pathway in TAM and promote the secretion of cathepsin, which is exacerbated by the inhibition of SHP2." (PMID 38747738, 2024). "In three genotypes of ROP16 overexpressing primary lung adenocarcinoma cells, we observed similar results to A549 for the phosphorylation of STAT3 by ROP16." (PMID 39174877, 2024). "CD109 acts as a pro-metastatic factor in lung adenocarcinoma by activating the JAK/STAT3 signaling pathway, which is also integral to inflammation and immune responses." (PMID 39990858, 2024). "Overexpression of STAT3 partially reversed the decrease in the mRNA and protein levels of EME1 in FIBP-deficient lung adenocarcinoma cells, indicating that FIBP controls the expression of EME1 in a STAT3-dependent manner." (PMID 37564211, 2023). "A clear endogenous interaction between FIBP and STAT3 was also observed in lung adenocarcinoma cells." (PMID 37564211, 2023). "Radiation induced senescence by increasing the expression of STAT3 and autophagic flux, such as Beclin1 and LC-3 II in lung adenocarcinoma cells." (PMID 36834846, 2023). "CD47 and p-STAT3 protein levels were consistently upregulated, and miR-34a was downregulated in the lung adenocarcinoma samples compared with the paired normal controls, regardless of KRAS mutation status." (PMID 36413402, 2023). "When STAT3 is overexpressed in alveolar type II cells, severe pulmonary inflammation takes place, which results in the spontaneous formation of lung adenocarcinoma in mice." (PMID 36672335, 2023). "It has been reported that nicotine promotes lung adenocarcinoma cell proliferation and migration via the α5nAChR/STAT3/NLRP3 inflammasome (nucleotide-binding and oligomerization domain-like receptors family) axis." (PMID 36770805, 2023).
lung adenocarcinoma (continued). "Here, we revealed that FIBP associates with STAT3 to stimulate its transcriptional activity, which consequently induces the expression of EME1, thereby driving lung adenocarcinoma radioresistance." (PMID 37564211, 2023). "Another study reported miR-139/Stat3 axis was involved in osteoclastogenesis in lung adenocarcinoma microenvironment." (PMID 36927608, 2023). "In lung adenocarcinomas, STAT3 can be activated by mutant EGFR via driving the expression of the IL-6 cytokine, which activates the gp130/JAK signaling pathway, while blocking this pathway will repress cell-cycle progression, cell growth, and tumorigenesis." (PMID 36557902, 2022). "PCNP can regulate the progression of human lung adenocarcinoma cells via the STAT3/5 and PI3K/Akt/mTOR signaling pathways." (PMID 36591491, 2022). "Gene correlation analyses of TCGA data revealed that several genes associated with p38-MAPK and JAK/STAT3 signaling were strongly positively correlated with AIF-1 expression in lung SCC and lung adenocarcinoma." (PMID 36520870, 2022). "In human lung adenocarcinoma cell lines, CD109 overexpression was associated with the ability of migration and metastasis by activating the Jak-Stat3 signaling." (PMID 36712866, 2022). "UBE alone or in combination with PEM also inhibited the JAK2/STAT3 signaling pathway in lung adenocarcinoma cells." (PMID 35789603, 2022). "Recently, Wu and colleagues demonstrated that lncRNAs LEISA accelerated the proliferation and inhibited apoptosis of lung adenocarcinoma cells in vitro and in vivo by facilitating STAT3 to transcriptionally activate IL-6." (PMID 35740511, 2022). "MiR-29B-3p regulates STAT3 in lung adenocarcinoma cells, according to Liu's research, and STAT3 can boost lung adenocarcinoma cell proliferation while inhibiting apoptosis." (PMID 35113040, 2022). "The lncRNA HOXA11-AS acts via miR-454–3p and Stat3 to promote cisplatin resistance in lung adenocarcinoma." (PMID 34868237, 2021). "Here, the authors identify VAL (Vimentin associated lncRNA) to be directly induced by AKT/STAT3 signaling and report a lncRNA-mediated mechanism for active AKT-driven EMT-independent lung adenocarcinoma metastasis." (PMID 33046716, 2020). "Next, we validated that expression levels of STAT3 were negatively correlated with progression‐free survival time in patients with lung adenocarcinoma." (PMID 32022328, 2020). "FASN has been previously related to AKT/ERK/EGFR signaling pathways and the inhibition of the transcription factor STAT3 in lung adenocarcinomas." (PMID 32438613, 2020). "Taken together, the results indicate that PCNP modulates apoptosis via STAT3/5 pathway in human lung adenocarcinoma cells." (PMID 30872582, 2019). "We have also demonstrated that YAP1 induces STAT3 phosphorylation in lung adenocarcinoma cells by increasing expression of interleukin-6 (IL-6) (manuscript under review)." (PMID 31137841, 2019). "Our study elucidates that PCNP can regulate the procession of human lung adenocarcinoma cells via STAT3/5 and PI3K/Akt/mTOR signaling pathways." (PMID 30872582, 2019). "Taken together, these observations suggest that SOCS2 is involved in the regulation of IGF1R-mediated EMT of lung adenocarcinoma cells, which is probably dependent on the STAT3 and STAT5 pathway." (PMID 29559623, 2018). "The data demonstrated that ALT inhibited constitutive as well as inducible STAT3 activation in NCI-H1650 lung adenocarcinoma cells in a similar fashion." (PMID 28740138, 2017). "The results were in agreement with earlier studies that postulated urethane induce over expression of key molecules such as NF-κB, Stat3, pStat3; IL-1β, those play a major role in chronic inflammation and lung adenocarcinoma." (PMID 28240047, 2017). "Pretreatment with the p38 inhibitor SB203580, increased expression of p-STAT3 in the lung adenocarcinoma cell line A54934 indicating that STAT3 was downstream of the ERK and p38 signaling pathways." (PMID 28592840, 2017).
lung adenocarcinoma (continued). "For example, increased secretion of IL-11 from CAFs treated with cisplatin mediates lung adenocarcinoma cell chemoresistance through paracrine signalling of the IL-11/IL-11R/STAT3 pathway." (PMID 29176691, 2017). "IL‐6 also induces EMT in vitro in immortalized epithelial oral cells, in a JAK2/STAT3/Snail1‐dependent way, in lung adenocarcinoma cells (in a STAT3‐Snail1‐dependent fashion) and in NSCLC cells." (PMID 28599100, 2017). "Inhibition of STAT3 activity was reported to induce apoptosis in lung adenocarcinoma cells via IL6/JAK2/STAT3 signalling pathway." (PMID 28427199, 2017). "Mutant EGFR genes have been reported to upregulate IL-6 and then activate the gp130/JAK/STAT3 pathway in primary human lung adenocarcinomas." (PMID 27362942, 2016). "In conclusion, chemotherapy-induced IL-11 upregulation in CAF promotes lung adenocarcinoma cell chemoresistance by activating IL-11R/STAT3 anti-apoptotic signaling pathway." (PMID 27922075, 2016). "It is also agreed with our previous report that persistent activation of STAT3 induces adenocarcinoma in the lung, and STAT3 serves as a biomarker for lung adenocarcinoma in humans." (PMID 27531897, 2016). "Two STAT3 siRNAs decreased PD-L1 expression by 10–32% in two of the three KRAS-mutant lung adenocarcinoma cell lines (p < 0.05), while the PI3K inhibitor LY294002 (40 μM) did not change the expression level." (PMID 27846317, 2016). "We subjected the three KRAS-mutant lung adenocarcinoma cell lines to STAT3 RNAi, and PD-L1 expression decreased in two of them, NCI-H1373 and NCI-H441, but not in NCI-H358 cells, at both protein and mRNA levels." (PMID 27846317, 2016). "In summary, this study showed that PD-L1 expression is regulated by MAPK and partially by STAT3 signaling in KRAS-mutant lung adenocarcinoma cell lines." (PMID 27846317, 2016). "We have reported that persistent activation of the STAT3 signaling pathway induced adenocarcinoma formation in the lung, and STAT3 serves as a biomarker for lung adenocarcinoma." (PMID 27531897, 2016). "Here we demonstrate that STAT3 plays an unexpected tumour-suppressive role in KRAS mutant lung adenocarcinoma (AC)." (PMID 25734337, 2015). "Here the authors show that STAT3 acts as a tumour suppressor in a mouse model of Kras-driven lung adenocarcinoma." (PMID 25734337, 2015). "To delineate this, we found studies reporting a persistent activation of STAT3 (pSTAT3) in nearly 50% of lung adenocarcinomas." (PMID 25466244, 2014). "Metformin can inhibit IL-6 induced EMT by blocking STAT3 phosphorylation, suggesting a potential clinical use of metformin in the treatment of lung adenocarcinoma." (PMID 24789104, 2014). "In this study, we showed that IL-6 was involved in EMT and metastasis, via induction of STAT3 phosphorylation in lung adenocarcinoma cells, by in vitro IL-6 stimulation experiments, clinical correlation analysis and xenograft experiments." (PMID 24789104, 2014). "In conclusion, we demonstrated that enhanced IL-6 production, via STAT3 phosphorylation, was one of the underlying mechanisms of EMT and metastasis in lung adenocarcinoma." (PMID 24789104, 2014). "In a patient cohort of 204 lung adenocarcinoma patients, STAT3 and CYP1B1 expression correlated with IDO1 expression." (PMID 24657910, 2014). "Autocrine IL-6-induced Stat3 activation has been implicated in tumor metastasis and the formation of MPE in lung adenocarcinoma." (PMID 24086497, 2013). "In summary, we showed that TF expression plays a pivotal role in the pathogenesis of MPE generation via regulating of tumor metastasis and vascular permeability in lung adenocarcinoma bearing activated Stat3." (PMID 24086497, 2013). "We previously found constitutively activated Stat3 promotes tumor metastasis of lung adenocarcinoma; therefore, we sought to investigate the role of TF in lung metastasis subsequently." (PMID 24086497, 2013).